RNU6-1216P (RNA, U6 small nuclear 1216, pseudogene)
Gene: Small nuclear RNA gene on chromosome 2 (69,182,877 to 69,182,983, forward strand). Ensembl gene ENSG00000199460.
Homologues: Orthologues: chimpanzee U6 (98% identical), macaque U6 (96% identical). Paralogues in human: RNU6-43P (93% identical), RNU6-49P (91% identical), RNU6-11P (90% identical), RNU6-37P (90% identical), RNU6-24P (89% identical), RNU6-25P (89% identical), RNU6-727P (89% identical), RNU6-97P (89% identical), RNU6-1 (88% identical), RNU6-1122P (88% identical), RNU6-12P (88% identical), RNU6-13P (88% identical), and 1290 more.